PEX6 (peroxisomal biogenesis factor 6)
Description:
Component of the PEX1-PEX6 AAA ATPase complex, a protein dislocase complex that mediates the ATP-dependent extraction of the PEX5 receptor from peroxisomal membranes, an essential step for PEX5 recycling. Specifically recognizes PEX5 monoubiquitinated at 'Cys-11', and pulls it out of the peroxisome lumen through the PEX2-PEX10-PEX12 retrotranslocation channel. Extraction by the PEX1-PEX6 AAA ATPase complex is accompanied by unfolding of the TPR repeats and release of bound cargo from PEX5.
Synonyms: PAF-2; PXAAA1; HMLR2; PAF2; PBD4A; PDB4B
Tractability: PROTAC: ubiquitination databases record sites on it; its protein half-life has been measured.
Safety:
Unwanted effects reported when the protein is acted on. In parentheses: how it was acted on, where the effect was seen, and who reports it.
hematological toxicity (source: ClinPGx)
Gene: Protein-coding gene on chromosome 6 (42,959,717 to 42,979,243, reverse strand). Ensembl gene ENSG00000124587.
Subcellular location: Cytoplasm, cytosol; Peroxisome membrane; Cell projection, cilium, photoreceptor outer segment
Subcellular location (Human Protein Atlas): Golgi apparatus; Cytosol
Pathways (Reactome):
Protein localization: Peroxisomal protein import
Gene Ontology:
Molecular function: ATP binding; ATP hydrolysis activity; membrane protein dislocase activity; protein binding; protein-containing complex binding; ubiquitin-modified protein reader activity
Biological process: peroxisome organization; protein import into peroxisome matrix, receptor recycling; protein import into peroxisome matrix, translocation; protein stabilization; protein targeting to peroxisome; protein unfolding
Cellular component: ATPase complex; cytoplasm; cytosol; peroxisomal membrane; peroxisome; photoreceptor cell cilium; photoreceptor outer segment
Genetic constraint (gnomAD): Loss-of-function variants: 55 observed, 86.15 expected, observed/expected ratio (o/e) 0.64, 90% interval 0.51 to 0.8. The upper end of that interval is the gene's LOEUF score, 0.8, which puts it in group 3 of 6, group 1 being the genes least tolerant of losing a copy. Missense variants: 1,099 observed, 1,228.3 expected, observed/expected ratio (o/e) 0.89, 90% interval 0.85 to 0.94. Synonymous variants: 519 observed, 522.29 expected, observed/expected ratio (o/e) 0.99, 90% interval 0.92 to 1.07.
Gene-disease validity (ClinGen):
ClinGen rates the evidence that PEX6 causes each of these diseases.
peroxisome biogenesis disorder (autosomal recessive): Definitive.
Homologues: Orthologues: chimpanzee PEX6 (99% identical), macaque PEX6 (94% identical), dog PEX6 (92% identical), pig PEX6 (91% identical), mouse Pex6 (88% identical), rat Pex6 (87% identical), guinea pig PEX6 (87% identical), rabbit PEX6 (84% identical), zebrafish pex6 (46% identical), tropical clawed frog PEX6 (44% identical), Drosophila melanogaster Pex6 (28% identical), Caenorhabditis elegans prx-6 (22% identical). Paralogues in human: PEX1 (23% identical), NVL (22% identical), VCP (21% identical), AFG2A (21% identical), AFG2B (21% identical).
Diseases named in the same sentence as PEX6 in open-access papers:
PEX6 is named in the same sentence as 43 diseases in open-access papers, as found by Europe PMC text mining. Sharing a sentence is not in itself a finding about the gene and the disease. The quoted sentences say what the papers report.
peroxisome biogenesis disorder (20 papers, 2011 to 2025). "Pathogenic variants in the PEX6 gene result in Heimler syndrome 2 (OMIM# 616,617), Zellweger (OMIM: 614,862), and Peroxisome biogenesis disorder 4B (OMIM# 614,863)." (PMID 40100472, 2025). "Other studies have reported PEX6 mutations to be associated with Peroxisome biogenesis disorders, along with hearing impairment and retinitis pigmentosa." (PMID 38674429, 2024). "Whereas, the monoallelic c.1802G > A (p.Arg601Gln) variant in the PEX6 gene has been associated with Peroxisome biogenesis disorders." (PMID 38956727, 2024). "In humans, mutations causing dysfunction in PEX1, PEX6, and PEX26—the human equivalents to yeast Pex1, Pex6, and Pex15—are the most prevalent cause of rare genetic disorders called peroxisome biogenesis disorders (PBDs)." (PMID 35805150, 2022). "Since mutations in PEX1 and PEX6 cause the majority of known cases of peroxisome biogenesis disorders such as Zellweger syndrome, insights into Pex1/Pex6 structure and function are important for understanding peroxisomes in human health and disease." (PMID 35805150, 2022). "WES Results & cDNA Analysis: WES identified a heterozygous variant in PEX6, c.1802G > A: p.(R601Q) previously associated with Heimler Syndrome, a mild peroxisomal biogenesis disorder (OMIM 616617)." (PMID 33776059, 2021). "Of relevance, mutations in two REM components, PEX1 and PEX6, have been shown to be the most frequent cause of peroxisomal biogenesis disorders accounting for 76% of all cases." (PMID 31652724, 2019). "Recessive PEX6 variants are associated with Heimler syndrome 2, a recessive peroxisome disorder characterized by sensorineural hearing loss, amelogenesis imperfecta and nail abnormalities, with or without visual defects (MIM #616617)." (PMID 30675382, 2019). "Altogether, our findings suggest a novel regulatory mechanism for PEX1/PEX6 hexamer assembly and highlight the potential of protein stabilization as a therapeutic strategy for peroxisome biogenesis disorders arising from the G843D mutation and other PEX1 hypomorphs." (PMID 40158855, 2025). "However, molecular analysis for one patient identified a pathogenic variant in PEX6, which is associated with peroxisomal diseases, specifically Zellweger spectrum disorder, and another was found to carry a COL4A1 variant associated with Stickler syndrome." (PMID 40114034, 2025). "The AAA-ATPase Pex1/Pex6 drives protein import into peroxisomes and is thus a key step in peroxisome formation and a common culprit for peroxisome biogenesis disorders." (PMID 35805150, 2022). "Heimler syndromes 1 and 2 are at the mildest end of the PBD spectrum, and are caused by pathogenic variants in PEX1 and PEX6, respectively." (PMID 33396879, 2020). "Heimler syndromes 1 and 2 arise from pathogenic variants in PEX1 and PEX6, respectively, which lead to impaired peroxisome biogenesis." (PMID 33396879, 2020). "Pex1 and Pex6 form a heterohexameric motor essential for peroxisome biogenesis and function, and mutations in these AAA-ATPases cause most peroxisome-biogenesis disorders in humans." (PMID 29321502, 2018). "Four of 30 SAPs in PEX6 (OMIM:601498) are FN with “Peroxisome biogenesis disorder/Zellweger syndrome” HGMD annotations." (PMID 27468419, 2016). "Pex1 and Pex6 were originally identified as genes necessary for yeast to grow on oleate, which requires peroxisomes, and were subsequently recognized as dysfunctional in humans with certain peroxisome biogenesis disorders." (PMID 35805150, 2022). "The connected component of peroxisomal disorders expressed in the hypothalamus consists of PEX19, PEX10, PEX6, and PEX7." (PMID 27748412, 2016). "To test if the induction of peroxisomal β-oxidation by BF caused the reduction in C26:0 levels, we incubated fibroblasts from patients with a peroxisomal biogenesis disorder (PEX1, PEX6 and PEX26) with BF and measured the effect on D3-C26:0 de novo synthesis." (PMID 22447153, 2012).
Zellweger syndrome (13 papers, 2011 to 2025). "Molecular testing identified PEX6 gene compound heterozygous mutations, supporting the Zellweger spectrum disorder diagnosis in this patient." (PMID 27779215, 2016). "Approximately 80% of PBD patients are classifiedin the Zellweger syndrome spectrum, which is generally caused by mutations in the PEX1, PEX6, PEX10, PEX12, or PEX26 genes." (PMID 33912394, 2021). "In Zellweger spectrum disorder, increased expression of peroxisomal biogenesis factor 6 (PEX6) results from a deletion in the 3′UTR of PEX6, which eliminates the distal canonical PAS leaving only the shorter isoform produced from the remaining proximal PAS." (PMID 32560344, 2020). "Zellweger spectrum disorders (ZSDs), including archetypal Zellweger syndrome, neonatal adrenoleukodystrophy (NALD) and infantile Refsum disease (IRD), are PBDs caused by mutations in peroxin genes (PEX1, PEX2, PEX3, PEX5, PEX6, PEX10, PEX11β, PEX12, PEX13, PEX14, PEX16, PEX19 or PEX26)." (PMID 40949164, 2025). "Only 50 missense mutations (29.4%, PEX1 = 21/85, PEX6 = 27/76, PEX26 = 2/9) were reported to be associated with Zellweger syndrome, which has a severe early-lethal clinical presentation, while the remaining 70.6% of variants are truncating stop or frameshift defects." (PMID 31831025, 2019). "The absence of residual PEX6 protein should correlate with reduced numbers of enlarged peroxisomes and negligible matrix protein import observed in fibroblasts from Zellweger syndrome patients." (PMID 22894767, 2012).
hearing loss (3 papers, 2019 to 2025). "Functional validation is recommended to be carried out in any future study for the variants detected in MYO3A, KCNQ1, PEX6, and TMC1 genes to provide stronger evidence for the pathogenicity of these variants and more robust support for their proposed role in hearing loss." (PMID 40100472, 2025).
Alzheimer disease (2 papers, 2020 to 2024). A progressive, neurodegenerative disease characterized by loss of function and death of nerve cells in several areas of the brain leading to loss of cognitive function such as memory and language. "The PEX6 missense variant, rs1129187, has been associated with Alzheimer’s disease in APOE ε4 carriers." (PMID 38674429, 2024).
amelogenesis imperfecta (2 papers, 2025 to 2026). Amelogenesis imperfecta (AI) represents a group of developmental conditions affecting the structure and clinical appearance of the enamel of all or nearly all the teeth in a more or less equal manner, and which may be associated with morphologic or biochemical changes elsewhere in the body. "It is caused by hypomorphic mutations in peroxisomal assembly genes, most commonly PEX1 and PEX6, and is characterized by sensorineural hearing loss, amelogenesis imperfecta, and retinal dystrophy." (PMID 42074478, 2026).
Ataxia (2 papers, 2024 to 2025). Ataxia refers to impaired coordination of voluntary muscle movement. "Severe alleles in PEX genes lead to severe clinical presentations, but in recent years, the mild presentations due to PEX mutations have expanded from phenotypes labeled as “infantile Refsum disease” to include atypical ataxia in PEX16 and Heimler syndrome in PEX1 and PEX6." (PMID 39605732, 2024).
Retinal dystrophy (2 papers, 2019 to 2026). Retinal dystrophy is an abnormality of the retina associated with a hereditary process. "Furthermore, at least one mutation in one patient affects the AAA-ATPase region (PEX1 and PEX6) or PEX6 binding site (PEX26) when HS patients have retinal dystrophy." (PMID 31831025, 2019).
ciliopathy (1 paper, 2023). A genetic disorder of the cellular cilia or the cilia anchoring structures, the basal bodies, or of ciliary function. "In addition to the CPLANE genes, our search uncovered a number of additional ciliopathy genes associated with multi-systemic, brain, kidney, and eye ciliopathies (Cep135, Innp5e, Pex6, Togaram1)." (PMID 36737727, 2023).
Hyperoxaluria (1 paper, 2024). Increased excretion of oxalates in the urine. "It has been associated with hyperoxaluria with NL and NC with variants in PEX1, likely with variants in PEX5, and possibly with variants in PEX3, PEX6, PEX 10, PEX 12, PEX13, PEX14, PEX16, PEX19, and PEX26." (PMID 38606357, 2024). "It has been associated with hyperoxaluria with NL and NC with variants in PEX1 and PEX3, likely with variants in PEX5, and possibly with variants in PEX6, PEX7, PEX10, PEX11, PEX12, PEX13, PEX16, and PEX26." (PMID 38606357, 2024).
hypothyroidism (1 paper, 2021). Abnormally low levels of thyroid hormone. "Conversely, hypothyroidism induced a strong decrease in Pex6 protein expression, which did not affect catalase import, as we demonstrated by CAT immunogold labelling." (PMID 34571897, 2021).
microphthalmia (1 paper, 2023). Congenital or developmental anomaly in which the eyeballs are abnormally small. "A similar search of DR17 using the term microphthalmia resulted in 22 genes significant for the small eyes phenotype: Aldh1a3, Aff4, Bmp4, Cdk4, Cox6b1, Cxcr4, Dync1li1, Eef1d, Fgd1, Gne, Grh12, Mab21l2, Maf, Med13l, Mllt10, Mthfd2, Pex6, Phgdh, Ssr1, Stim1, Tdo2, and Vps26c." (PMID 36737727, 2023).
Perrault syndrome (1 paper, 2023). Perrault syndrome (PS) is characterized by the association of ovarian dysgenesis in females with sensorineural hearing impairment. "In addition to well-established Perrault syndrome genes involved in mitochondrial function, recent studies have described causative variants in non-mitochondrial genes including HSD17B4, GGPS1 and PEX6 in patients presenting with clinical features overlapping with Perrault syndrome." (PMID 37148394, 2023).
prostate carcinoma (1 paper, 2016). A carcinoma that arises from epithelial cells of the prostate gland. "One presently identified eQTL for the PEX6 gene was rs10948059, which had been associated with prostate cancer from previous association studies." (PMID 28033303, 2016). "Since the nucleotide variants were revealed as a strong eQTL for PEX6 gene from the current study (P = 6.98 × 10−108), the variants associated with prostate cancer might be identified through expressional change in PEX6." (PMID 28033303, 2016). "The results imply that variants associated with prostate cancer can be identified through expressional change in the PEX6 gene, but not in the overlapped glycine N-methyltransferase gene which had been considered as a candidate gene." (PMID 28033303, 2016).
retinal degeneration (1 paper, 2024). Degeneration of the retina. "These high confidence variants were found in ABCA4, CERKL, MAK, PEX6 and RDH12 genes associated with retinal degeneration, that could be sufficient to cause pathology." (PMID 39365799, 2024).
cancer (3 papers, 2016 to 2025). A tumor composed of atypical neoplastic, often pleomorphic cells that invade other tissues. "In conclusion, the current study revealed novel eQTLs for SNHG5 and PEX6 genes in chromosome 6.Nucleotide substitutions of the eQTLs might be candidate factors for a variety of cancers by regulating expression of the 2 genes." (PMID 28033303, 2016). "Little is known about the function of the other H2Bub1-dependent peroxisome-related genes PEX6 and PMVK in cancers." (PMID 40597205, 2025).
PEX6 also shares sentences with these, for which no sentence is quoted: Zellweger spectrum disorders (5 papers); Refsum disease (2); Autosomal recessive spastic paraplegia type 46 (1); Breast Invasive Carcinoma (1); developmental delay (1); enamel hypoplasia (1); Fanconi anemia (1); genetic disorders (1); infection (1); Leber congenital amaurosis (1); Leber congenital amaurosis with early-onset deafness (1); lung carcinoma (1); lymphoma (1); macular degeneration (1); melanoma (1); microcephaly (1); Nail dystrophy (1); neurodegenerative disease (1); Niemann Pick type C disease (1); osteoporosis (1); retinitis pigmentosa (1); rhizomelic chondrodysplasia punctata type 1 (1); Seckel syndrome (1); sensorineural hearing loss (1); spinocerebellar ataxia type 28 (1); Stickler syndrome (1); tumor (1); Usher syndrome (1).